FGF23 (fibroblast growth factor 23)
Diseases named in the same sentence as FGF23 in open-access papers (continued):
Sharing a sentence is not in itself a finding about the gene and the disease.
heart failure (continued). "Serum FGF23 levels are increased in children with heart failure." (PMID 26483756, 2015). "Higher levels of FGF23 are independently associated with inflammation in patients with CKD and high RDW values have been associated with plasma markers of inflammation in a large cohort of unselected adult outpatients and in patients with heart failure." (PMID 26079688, 2015). "The majority of deaths were due to cardiovascular disease and there was an association between FGF23 and heart failure and stroke, but not with myocardial infarction." (PMID 23587028, 2013). "However, the CARE FOR HOMe study revealed a more nuanced association, with FGF23 being linked to future decompensated heart failure but not to incident atherosclerotic events in stage 2–4 CKD." (PMID 41561945, 2025). "Our study suggests that bone may also be a source of FGF23 independent of heart failure, e.g. in inflammatory conditions associated with enhanced production of oncostatin M." (PMID 37225713, 2023). "Importantly, in heart failure, oncostatin M stimulates cardiac FGF23 production." (PMID 37225713, 2023). "In a sub study of TOPCAT (Treatment of Preserved Cardiac Function Heart Failure with an Aldosterone Antagonist Trial), GDF-15 was labeled as an “intermediary metabolism” protein clustering with proteins associated with mineral metabolism including fibroblast growth factor-23 and osteoprotegerin." (PMID 36844723, 2023). "Furthermore, the sample size in FGF23 test was relatively small, and the decrease of FGF23 did not adequately indicate a decrease in heart failure risk." (PMID 37593148, 2023). "Thus, upacicalcet might prevent cardiovascular mortality and heart failure by decreasing serum FGF23 concentrations, like cinacalcet." (PMID 37696667, 2023). "Mechanistically, FGF23-mediated activation of FGFR4 causes mitochondrial dysfunction, suggesting that early pharmacologic inhibition of FGFR4 might serve as novel therapeutic intervention to prevent development of LVH and heart failure in patients with CKD." (PMID 38196615, 2023). "Importantly, FGF23 may predict clinical outcome in patients with acute and established heart failure (HF)." (PMID 35160052, 2022). "This possibility is further supported by recent human studies showing that circulating FGF23 levels were associated with the severity of heart failure, but these levels did not change after acute injection of isotonic saline in patients with arterial hypertension." (PMID 34765890, 2021). "Finally, the lack of data on newer markers of phosphate homeostasis (i.e., fibroblast growth factor 23) or data on echocardiogram parameters precludes any inference on the potential relationship of FeP and heart failure and future efforts are required to shed light on this aspect." (PMID 31336909, 2019). "The Ang II and FGF-23 endocrine network may help explain why elevated FGF-23 is associated with enhanced responses to angiotensin-converting enzyme inhibitor (ACEi) therapy in patients with heart failure but without CKD79,80." (PMID 30120363, 2018). "However, myocardial FGF23 gene expression levels and FGF23 immunostaining are not increased in ADHF patients, suggesting that the myocardium does not contribute to elevated circulating FGF23 levels in ADHF and that FGF23 plays roles in heart failure in an endocrine manner." (PMID 27803896, 2016). "In conclusion, our study showed that TAC-induced heart failure leads to cortical bone osteopenia in a PTH- and FGF23-independent manner in mice." (PMID 41515999, 2025). "Notably, none of the studies in patients with end-stage organ failure used activated vitamin D, indicating that the severity of kidney/heart failure may be even more important for the vitamin D-induced increase in FGF23 than the type of vitamin D (native or activated vitamin D)." (PMID 32855522, 2021).
heart failure (continued). "Fibroblast growth factor 23 is considered to be a major contributor to the development of LVH, heart failure, atrial fibrillation, and increased cardiovascular and all-cause mortality in CKD and non-CKD populations." (PMID 34778257, 2021). "These insights in patients with stable ischemic heart disease were also noticed in heart failure patients, who only benefited from ACE inhibition in case of elevated FGF23 levels." (PMID 31540546, 2019). "With its biological toxicity to the cardiovascular system and the kidneys, FGF23 appears to be one of the key drivers in the cardio-renal connection that accelerates the progression of CKD and heart failure as well as the progression of cardiorenal syndrome." (PMID 30200452, 2018). "We noted that myocardial and plasma FGF23 and FGF receptor 4 were increased in mice with heart failure as well as in cultured adult mouse cardiac fibroblasts (AMCFs) exposed to angiotensin II, phenylephrine, soluble fractalkine." (PMID 27579618, 2016). "Recent studies have reported direct FGF-23 effects on the heart myocardium, and elevated plasma levels of FGF-23 have been associated with negative CVD outcomes such as arrhythmias and heart failure." (PMID 40612843, 2025). "Previous studies have established a connection between elevated FGF23 concentration and death, as well as heart failure in non-ACS populations." (PMID 38846254, 2024). "FGF-23 level was increased in ULMCAD patients with previous heart failure (P = 0.046) by contrast to those without." (PMID 36132198, 2022). "There are clear clinical data illustrating an association of increased FGF23 and reduced αKlotho with uremic cardiomyopathy in patients with CKD, and in heart failure and AF in subjects without known CKD." (PMID 32212912, 2020). "In patients with early CKD, FGF23 levels are significantly higher in patients with heart failure than without heart failure." (PMID 30200452, 2018). "Of note, FGF-23 turned out to be a stronger predictor of heart failure decompensation rather than of acute atherosclerotic cardiovascular events." (PMID 30013515, 2018). "Recent studies indicate that FGF23 is also expressed in the heart, and markedly enhanced in various clinical and experimental settings of cardiac remodeling and heart failure independent of preserved or reduced renal function." (PMID 29892269, 2018). "Furthermore, the circulating concentrations of FGF23 are significantly higher in non-surviving patients with myocardial infarction and heart failure." (PMID 36909314, 2023). "Moreover, FGF23 is expressed by cardiomyocytes, and cardiac FGF23 expression is increased in uremic rats, transverse aortic constriction-operated mice or mice after myocardial infarction as well as in patients with CKD and heart failure." (PMID 31540546, 2019). "Hence, FGF23 targets the heart directly by acting on FGFR4 with subsequent triggering of the PLCγ/calcineurin/NFAT signaling pathway, which promotes cardiac hypertrophy, fibrosis, and heart failure." (PMID 30909513, 2019). "However, myocardial infarction is a rare event in dogs and cats, and the relationship between FGF‐23 in CKD and heart failure has not been determined." (PMID 34418162, 2021). "While FGF-23 does not appear to be a predominant factor for subclinical myocardial injury in CRIC subjects without CVD, it may yet prove crucial in the development of heart failure in this cohort via induction of LVH." (PMID 24148285, 2013).
X-linked hypophosphatemia (131 papers, 2009 to 2026). X-linked hypophosphatemia (XLH) is a hereditary renal phosphate-wasting disorder characterized by hypophosphatemia, rickets and/or osteomalacia, and diminished growth. "X-linked hypophosphatemia (XLH) is a rare genetic condition in which excess fibroblast growth factor 23 causes renal phosphate wasting, leading to skeletal morbidities." (PMID 42038817, 2026). "Renal hypophosphatemia, depending on the mechanism, is divided into PTH-dependent (e.g., primary hyperparathyroidism), FGF23-dependent (e.g., X-linked hypophosphatemia), and intrinsic renal hypophosphatemia (e.g., Fanconi syndrome)." (PMID 41008628, 2025). "Renal causes can be divided into intrinsic renal causes (e.g., Fanconi syndrome), parathyroid hormone-dependent causes (e.g., calcipenic rickets), and fibroblast growth factor 23-dependent causes (e.g., X-linked hypophosphatemia)." (PMID 41008628, 2025). "X-linked hypophosphatemia (XLH) is a phosphate-wasting disorder caused by increased fibroblast growth factor 23 (FGF23); it leads to skeletal deformities, muscle weakness, and pain." (PMID 41030383, 2025). "X-linked hypophosphatemia (XLH) is an X-linked dominant condition where fibroblast growth factor-23 (FGF23) excess leads to hypophosphatemic rickets, lower limb bowing, and musculoskeletal pain." (PMID 41445553, 2025). "It was approved in 2018 for the treatment of X-linked hypophosphatemia and acts by blocking the function of fibroblast growth factor 23 (FGF23), increasing renal tubular phosphate reabsorption and normalizing serum phosphate levels." (PMID 41219972, 2025). "Then, our team suspected hypophosphatemic rickets, including X-linked hypophosphatemia, vitamin D deficiency, or a tumor producing FGF23." (PMID 39416269, 2024). "High levels of FGF-23 have been observed in tumors from patients with oncogenic osteomalacia and in X-linked hypophosphatemia." (PMID 39803160, 2024). "X-linked hypophosphatemia (XLH) is a genetic disease that results in excessive FGF23, chronic hypophosphatemia, and musculoskeletal abnormalities, with affected patients experiencing symptoms such as bone pain, bone deformity, fracture, and pseudofracture." (PMID 39015507, 2024). "X-linked hypophosphatemia (XLH) is a rare genetic disorder that increases fibroblast growth factor 23 (FGF23)." (PMID 38542517, 2024). "Burosumab, a monoclonal antibody directed against the fibroblast growth factor 23 (FGF23), has been approved for the treatment of X-linked hypophosphatemia (XLH)." (PMID 38788147, 2024). "It is of special interest that the FGF23 assays can specifically be influenced by the new treatment for X-linked hypophosphatemia, burosumab." (PMID 35665817, 2023). "Blocking FGF23 became an effective therapeutic strategy in X-linked hypophosphatemia, but testing remains limited in autosomal recessive hypophosphatemic rickets (ARHR)." (PMID 37943605, 2023). "X-linked hypophosphatemia (XLH) is characterized by high serum fibroblast growth factor 23 (FGF23) levels, resulting in impaired 1,25-dihydroxyvitamin D3 (1,25D) production." (PMID 37490334, 2023). "Burosumab, a fully humanized FGF23-antibody, was recently approved for treatment of X-linked hypophosphatemia (XLH) and TIO and shown to be superior for treatment of XLH compared to conventional treatment." (PMID 35352187, 2022). "While there are several types of heritable FGF23-related hypophosphatemic rickets, X-linked hypophosphatemia (XLH) is the most prevalent one." (PMID 36531500, 2022). "Recently, burosumab, a human monoclonal antibody against FGF23, has been approved for the therapy of X-linked hypophosphatemia in children and adults, the most common heritable, genetically-determined form of FGF23-related hypophosphatemic disease." (PMID 35381903, 2022). "Secondly, it led to development of a novel therapy of X-linked hypophosphatemia with the use of a monoclonal blocking antibody to FGF23 (burosumab)." (PMID 35736431, 2022).
X-linked hypophosphatemia (continued). "X-linked hypophosphatemia is due to mutations in PHEX resulting in increased expression of FGF23 in bone and consecutive renal phosphate wasting and reduced calcitriol levels, as well as other so far poorly understood alterations." (PMID 35352187, 2022). "Burosumab is an antibody against FGF23 that is approved and therapeutically used in the treatment of X-linked hypophosphatemia." (PMID 35084563, 2022). "Burosumab, a monoclonal antibody FGF-23 inhibitor, has already been approved for treating X-linked hypophosphatemia and hypophosphatemic rickets." (PMID 35300523, 2022). "The uremic environment seems to prime the cardiomyocytes to FGF23 signaling since the left ventricular function was reported normal in patients suffering from increased FGF23 due to genetic causes and an animal model of x-linked hypophosphatemia." (PMID 34065339, 2021). "X-linked hypophosphatemia (XLH) is a form of rickets with low phosphate levels due to renal loss with increased fibroblast-growth factor-23 levels." (PMID 33669283, 2021). "An English-language search of PubMed, MEDLINE, and clinicaltrials.gov was performed using the terms burosumab, KRN23, X-linked hypophosphatemia, and FGF23 from January 2013 to February 2020 in March 2020." (PMID 34203792, 2021). "In contrast to CKD, X-linked hypophosphatemia is associated with low serum phosphate levels and FGF23 elevation and Klotho deficiency are less pronounced than in CKD patients." (PMID 31698866, 2019). "Currently, a fully human monoclonal IgG1 antibody, Burosumab, is under investigation for rare diseases with primary FGF23 excess and the clinical picture of phosphate-losing osteomalacia (X-linked hypophosphatemia)." (PMID 30013515, 2018). "Increased serumconcentrations of intact FGF23 are a hallmark of renal phosphate-wasting diseases such asADHR, X-linked hypophosphatemia (XLH), tumor-induced osteomalacia, or autosomal recessivehypophosphatemic rickets 1 (Martin,David, and Quarles 2012)." (PMID 29096595, 2017). "A novel mechanism involving autocrine and paracrine actions of fibroblast growth factor-23 contributes to the mineralization defect observed in Hyp, a mouse model for X-linked hypophosphatemia." (PMID 27035636, 2016). "Prospective trials have demonstrated safe, efficacious use of burosumab in the FGF23 excess disorders X-linked hypophosphatemia (XLH) and tumor-induced osteomalacia (TIO), leading to improved serum phosphate levels and skeletal outcomes without adverse gastrointestinal or renal side effects." (PMID 41480037, 2025). "Our study investigates the impact of FGF23 overexpression on SaOS-2 cells to elucidate its role in cellular stress and morphology, contributing to the understanding of skeletal pathologies like X-linked hypophosphatemia (XLH)." (PMID 39329699, 2024). "Finally, burosumab, a monoclonal antibody targeting FGF23, has been recently tested in patients with X-linked hypophosphatemia." (PMID 37658340, 2023). "In addition, burosumab, a fully humanized FGF23 antibody, was recently approved for treatment of X-linked hypophosphatemia (XLH) and tumor-induced osteomalcia (TIO)." (PMID 35352187, 2022). "Burosumab (KRN23) is an FGF23 neutralizing antibody that has been the subject of several recent clinical trials principally focused on the treatment of hypophosphatemic rickets in patients with X-linked hypophosphatemia (XLH)." (PMID 32547492, 2020). "Increased serum FGF23 has also been reported in X-linked hypophosphatemia (XLH)." (PMID 30374308, 2018). "However, in patients with X-linked hypophosphatemia, a rare disease of primary FGF23 excess, data on cardiac structure are inconsistent with respect to the development of LV hypertrophy." (PMID 25902817, 2015). "X-linked hypophosphatemia (XLH) is caused by PHEX gene variants that result in increased circulating levels of fibroblast growth factor 23 (FGF23)." (PMID 41777640, 2026).
X-linked hypophosphatemia (continued). "X-linked hypophosphatemia (XLH) is characterized by lifelong hypophosphatemia caused by excess circulating levels of FGF23 due to loss-of-function mutations in the PHEX gene." (PMID 40486045, 2025). "The most common inherited cause of FGF23-mediated hypophosphatemic osteomalacia is X-linked hypophosphatemia (XLH) secondary to a PV of the PHEX gene." (PMID 41445556, 2025). "X-linked hypophosphatemia (XLH) is a phosphate-wasting disorder mediated by increased fibroblast growth factor 23 (FGF23) activity." (PMID 41185884, 2025). "The most common genetic cause of FGF23-induced hypophosphatemic osteomalacia is X-linked hypophosphatemia (XLH), secondary to a pathogenic variant (PV) of the PHEX gene." (PMID 41445556, 2025). "X-linked hypophosphatemia (XLH) is a rare genetic disorder characterized by pathological elevations in the serum concentrations of fibroblast growth factor 23 (FGF23) caused by variants of the PHEX gene, leading to low levels of phosphate in the blood." (PMID 40358789, 2025). "Nevertheless, these findings are consistent with the role of FGF23 in bone metabolism and its dysregulation leading to skeletal pathologies like X-linked hypophosphatemia (XLH)." (PMID 39329699, 2024). "The article also notes that elevated levels of PKC activity in skeletal tissue are found in X-linked hypophosphatemia (XLH) models, while XLαs ablation reduces the FGF23 and phosphate phenotype in these mice." (PMID 37920253, 2023). "An inactivating PHEX gene mutation with the resultant accumulation of several mineralization-inhibiting proteins (e.g., FGF23) causes skeletal and dental morbidity in X-linked hypophosphatemia (XLH)." (PMID 36051396, 2022). "X-linked hypophosphatemia (XLH) is the most prevalent type of heritable fibroblast growth factor 23 (FGF23)-related hypophosphatemic rickets." (PMID 36531500, 2022). "X-linked hypophosphatemia (XLH) is a rare skeletal disorder associated with increased levels of fibroblast growth factor 23 (FGF23), resulting in skeletal deformities and short stature." (PMID 34705504, 2021). "Vitamin D and phosphates are the conventional therapy for X-linked hypophosphatemia (XLH), an FGF23-mediated disorder characterized by impaired renal tubular reabsorption of phosphate." (PMID 32204545, 2020). "X-linked hypophosphatemia (XLH) and tumor-induced osteomalacia (TIO) are characterized by alterations in phosphate metabolism due to elevated levels of fibroblast growth factor 23 (FGF23)." (PMID 41473242, 2025). "These mutants include a mouse model of X-linked hypophosphatemia (the Hyp mouse – a spontaneous mutation inactivating the PHEX enzyme) and a transgenic mouse model where the fibroblast growth factor 23 (FGF23) gene has been deleted (the Fgf23−/− mouse)." (PMID 40439195, 2025). "Burosumab, a monoclonal antibody that binds and inhibits FGF23 activity, was approved in 2018 for treatment of children and adults with X-linked hypophosphatemia (XLH), an X-linked dominant disorder due to increased serum fibroblast growth factor 23 (FGF23) concentration." (PMID 41210504, 2025). "The most frequent subtype is X-linked hypophosphatemia (XLH), caused by pathogenic variants in the PHEX gene, which elevate circulating FGF23 and suppress renal phosphate reabsorption and active vitamin D synthesis." (PMID 41375889, 2025). "X-linked hypophosphatemia (XLH) and tumor-induced osteomalacia (TIO) are rare disorders characterized by elevated levels of fibroblast growth factor 23 (FGF23), which affects phosphate homeostasis." (PMID 41473242, 2025). "FGF23 levels are significantly elevated in patients diagnosed with X-linked hypophosphatemia (XLH)." (PMID 38902808, 2024). "X-linked hypophosphatemia (XLH) is a rare, hereditary, progressive, renal phosphate-wasting disorder characterized by a pathological increase in FGF23 concentration and activity." (PMID 37752558, 2023).